ALK (ALK receptor tyrosine kinase)
Description:
Neuronal receptor tyrosine kinase that is essentially and transiently expressed in specific regions of the central and peripheral nervous systems and plays an important role in the genesis and differentiation of the nervous system. Also acts as a key thinness protein involved in the resistance to weight gain: in hypothalamic neurons, controls energy expenditure acting as a negative regulator of white adipose tissue lipolysis and sympathetic tone to fine-tune energy homeostasis (By similarity). Following activation by ALKAL2 ligand at the cell surface, transduces an extracellular signal into an intracellular response. In contrast, ALKAL1 is not a potent physiological ligand for ALK. Ligand-binding to the extracellular domain induces tyrosine kinase activation, leading to activation of the mitogen-activated protein kinase (MAPK) pathway. Phosphorylates almost exclusively at the first tyrosine of the Y-x-x-x-Y-Y motif. Induces tyrosine phosphorylation of CBL, FRS2, IRS1 and SHC1, as well as of the MAP kinases MAPK1/ERK2 and MAPK3/ERK1. ALK activation may also be regulated by pleiotrophin (PTN) and midkine (MDK). PTN-binding induces MAPK pathway activation, which is important for the anti-apoptotic signaling of PTN and regulation of cell proliferation. MDK-binding induces phosphorylation of the ALK target insulin receptor substrate (IRS1), activates mitogen-activated protein kinases (MAPKs) and PI3-kinase, resulting also in cell proliferation induction. Drives NF-kappa-B activation, probably through IRS1 and the activation of the AKT serine/threonine kinase. Recruitment of IRS1 to activated ALK and the activation of NF-kappa-B are essential for the autocrine growth and survival signaling of MDK. May function as regulator of gastric epithelial differentiation (By similarity).
Synonyms: CD246; ALK1; NBLST3
Tractability: Small molecule: an approved drug acts on it; a structure with a bound ligand is known; a high-quality ligand is known; it has a high-quality binding pocket; it belongs to a druggable protein family. Antibody: UniProt places it where antibodies can reach, with high confidence; its Gene Ontology location is reachable by antibodies, with high confidence; UniProt predicts a signal peptide or a membrane-spanning region; the Human Protein Atlas places it where antibodies can reach. PROTAC: it is named in the literature on targeted protein degradation; ubiquitination databases record sites on it; a small molecule that binds it is known. Other modalities: a drug acting on it is in phase 1 trials.
Target class: Enzyme; TKL protein kinase group; TKL protein kinase STKR family; TKL protein kinase STKR Type 1 subfamily; Protein Kinase; Kinase
Chemical probes: ALECTINIB (high quality), CERITINIB, CH5424802 analog, MS4078, PD080682, PD080931, PD080951, PD081023, PD081025, PD081049, PD081167, PD081253, PD081562, PD081693, PD081923, PD082218, PD082596, PD082722, PD083095, PD083137, and 30 more
Gene: Protein-coding gene on chromosome 2 (29,192,774 to 29,921,586, reverse strand). Ensembl gene ENSG00000171094.
Subcellular location: Cell membrane
Subcellular location (Human Protein Atlas): Plasma membrane
Pathways (Reactome):
Disease: ALK mutants bind TKIs; ASP-3026-resistant ALK mutants; NVP-TAE684-resistant ALK mutants; Signaling by ALK fusions and activated point mutants; alectinib-resistant ALK mutants; brigatinib-resistant ALK mutants; ceritinib-resistant ALK mutants; crizotinib-resistant ALK mutants; lorlatinib-resistant ALK mutants
Signal Transduction: MDK and PTN in ALK signaling; Signaling by ALK
Gene Ontology:
Molecular function: heparin binding; identical protein binding; protein binding; protein tyrosine kinase activity; receptor signaling protein tyrosine kinase activator activity; transmembrane receptor protein tyrosine kinase activity; ATP binding; protein kinase activity
Biological process: cell surface receptor protein tyrosine kinase signaling pathway; peptidyl-tyrosine autophosphorylation; phosphorylation; protein autophosphorylation; energy homeostasis; negative regulation of lipid catabolic process; neuron development; positive regulation of dendrite development; regulation of apoptotic process; regulation of cell population proliferation; regulation of neuron differentiation; signal transduction; nervous system development
Cellular component: extracellular exosome; plasma membrane; protein-containing complex; receptor complex; membrane
Genetic constraint (gnomAD): Loss-of-function variants: 77 observed, 165.7 expected, observed/expected ratio (o/e) 0.46, 90% interval 0.39 to 0.56. The upper end of that interval is the gene's LOEUF score, 0.56, which puts it in group 2 of 6, group 1 being the genes least tolerant of losing a copy. Missense variants: 2,033 observed, 2,154.7 expected, observed/expected ratio (o/e) 0.94, 90% interval 0.91 to 0.98. Synonymous variants: 940 observed, 860.69 expected, observed/expected ratio (o/e) 1.09, 90% interval 1.03 to 1.15.
Gene-disease validity (ClinGen):
ClinGen rates the evidence that ALK causes each of these diseases.
neuroblastoma, susceptibility to, 3 (autosomal dominant): Definitive.
Cancer hallmarks: invasion and metastasis (promotes); proliferative signalling (promotes); escaping programmed cell death (promotes or suppresses)
Homologues: Orthologues: chimpanzee ALK (99% identical), macaque ALK (98% identical), dog ALK (92% identical), rat Alk (87% identical), mouse Alk (87% identical), rabbit ALK (69% identical), guinea pig ALK (69% identical), tropical clawed frog ALK (59% identical), zebrafish alk (38% identical). Paralogues in human: LTK (29% identical), IGF1R (14% identical), INSR (13% identical), ROS1 (13% identical), INSRR (13% identical), FLT4 (12% identical), FLT1 (12% identical), KDR (12% identical), CSF1R (12% identical), PDGFRA (11% identical), MST1R (11% identical), AXL (11% identical), and 41 more.
Diseases named in the same sentence as ALK in open-access papers:
ALK is named in the same sentence as 622 diseases in open-access papers, as found by Europe PMC text mining. Sharing a sentence is not in itself a finding about the gene and the disease. The quoted sentences say what the papers report.
lung cancer (1,701 papers, 2008 to 2026). A malignant neoplasm involving the lung. "Previous studies have reported EGFR mutation rates in young lung cancer ranging from 32% to 46.9%, and ALK rearrangement rates from 6.3% to 19%, which are consistent with those reported in this study." (PMID 41002559, 2025). "The importance of sex and ALK mutation in our model is consistent with previous research highlighting gender differences in lung cancer incidence and the role of genetic alterations in cancer development." (PMID 39857011, 2025). "For lung cancer patients with ALK mutations, the effect of ALK inhibitor-targeted therapy seems to be far better than that of chemotherapy." (PMID 40071084, 2025). "A network meta-analysis showed that alectinib is proven to be the first choice for first-line and second-line treatment of advanced lung cancer with ALK mutations." (PMID 41002559, 2025). "More interestingly, overexpression of SPP1 is associated with poor outcomes in ALK fusion lung cancer patients." (PMID 40883281, 2025). "ALK gene abnormalities predominantly encompass fusions, point mutations, and amplifications, with EML4-ALK-positive non–small cell lung cancer representing a canonical example." (PMID 41614760, 2025). "Tumor-specific somatic mutations also contribute to VTE risk, such as ALK rearrangements increasing the risk in nonsmall cell lung cancer and IDH1 mutations decreasing the risk in gliomas." (PMID 39851266, 2025). "The study confirmed that the radiomics and machine learning analysis with KNN classifier can be method to predict early metastasis in stage III/IV lung cancer patients with specific driver gene mutation (ALK-positive)." (PMID 40606995, 2025). "In 2016, ExoDxTM Lung (ALK) became the first biomarker to successfully complete clinical trials, marking a milestone for EVs as disease diagnostic biomarkers by diagnosing lung cancer through the detection of EMLA-ALK mutations." (PMID 40183074, 2025). "Crizotinib, an anaplastic lymphoma kinase (ALK)/ROS1/c‐MET inhibitor, improves outcomes in ALK‐positive non‐small cell lung cancer (NSCLC) but can cause crizotinib‐associated renal cysts (CARCs), a rare yet clinically relevant adverse effect." (PMID 40542555, 2025). "The coverage of the molecular events underlying the development of ALK‐positive lung cancer and principles of targeted therapies then follows." (PMID 41213866, 2025). "ALK rearrangements are less common and have been identified in radon-induced lung cancers and are associated with sensitivity to ALK inhibitors, such crizotinib." (PMID 40427695, 2025). "At the molecular level, several studies have found that EGFR mutations and ALK rearrangements are less common in COPD-related lung cancer, with EGFR mutations showing an inverse relationship with the severity of airflow limitation." (PMID 40724620, 2025). "Resistance frequently arises during approved treatments, underscoring the need for further research to elucidate the molecular events and resistance mechanisms associated with ALK-positive lung cancer." (PMID 40873540, 2025). "This meta-analysis was designed to determine the diagnostic value of ctDNA for ALK rearrangement in lung cancer patients." (PMID 40853979, 2025). "Based on such fact, we conducted this meta-analysis to investigate the diagnostic accuracy of ctDNA in detecting ALK status of lung cancer patients." (PMID 40853979, 2025). "This is the first meta-analysis focusing on the diagnostic value of ALK rearrangement by ctDNA in lung cancer." (PMID 40853979, 2025). "Hyperactivation of this pathway enhances proliferation, survival, and metastasis in lung cancer, and has been implicated in resistance to ALK inhibitors." (PMID 40873540, 2025). "Targeted therapy for EGFR and ALK mutations in lung cancer is one of the most successful applications of multi-omics strategies in cancer treatment." (PMID 41269529, 2025).
lung cancer (continued). "Currently, some studies have reported an association between lung cancers with ALK and ROS1 rearrangements and an elevated risk of TEs." (PMID 40751559, 2025). "Previous studies have primarily explored the relationship between CT imaging features, EGFR mutations, and ALK rearrangements in patients with lung cancer, often focusing separately on qualitative or quantitative parameters." (PMID 41020204, 2025). "Anaplastic lymphoma kinase (ALK) gene rearrangement in lung cancer was first reported as the echinoderm microtubule-associated protein-like 4 (EML4)-ALK fusion gene in adenocarcinoma." (PMID 39781173, 2024). "Fusion with the echinoderm microtubule‐associated protein‐like 4 (EML4) is the most common ALK fusion in non‐small cell lung cancer (NSCLC)." (PMID 39188081, 2024). "We report a case of a patient with PMEC-predominant primary lung cancer combined with an ALK mutation." (PMID 39259069, 2024). "Lung cancer remains the most frequently diagnosed cancer and the leading cause of cancer-related death worldwide, with anaplastic lymphoma kinase (ALK) fusion mutations accounting for approximately 4%-9% of cases." (PMID 39800480, 2024). "In lung cancers, the most common rearrangement involves the fusion of the ALK gene with EML4 (echinoderm microtubule-associated protein-like 4)." (PMID 39199653, 2024). "Alterations in other cyclin-dependent kinase inhibitors such as CDKN2A have been reported in cutaneous squamous cell carcinomas associated with alterations in ALK in tumors such as lung cancer." (PMID 39273494, 2024). "The co-expression of PD-L1 and CD8 in EGFR-mutated or ALK-rearranged lung cancer serves as a biomarker for poor prognosis, correlating with a shorter OS." (PMID 38397899, 2024). "Inhibitors of the anaplastic lymphoma kinase (ALK) gene mutation are first-line treatments in patients with ALK-positive lung cancer." (PMID 39399468, 2024). "EML4 (echinoderm microtubule-associated protein-like 4)-ALK in lung cancer is an example of a well-known gene fusion involving a kinase-coding gene." (PMID 39518064, 2024). "PMEC combined with ALK mutation is an extremely rare primary lung cancer, and the diagnosis is mainly based on pathology, histology and immunohistochemistry." (PMID 39259069, 2024). "Lung cancer has been linked to over 90 distinct ALK fusion partners; however, compared to the most common ALK fusion variants, there is currently insufficient large-scale clinical evidence regarding the predictive value of unusual fusions." (PMID 39063924, 2024). "Drugs including ceritinib, alectinib, and brigatinib have been developed to treat cancers with mutations in the ALK gene, including lung cancer and NB, demonstrating a higher efficacy than older drugs like crizotinib, especially against specific ALK mutations." (PMID 39101440, 2024). "ALK mutations in lung cancers are often the result of genetic rearrangements, leading to the formation of fusion proteins with oncogenic activity." (PMID 39199653, 2024). "We propose the consideration of this dual-target approach, specifically employing ensartinib and pralsetinib, in managing RET-rearranged lung cancer coexisting with targetable ALK mutations." (PMID 38698976, 2024). "In EGFR-mutated and ALK-rearranged lung cancer cell lines, MCL1 translocates to the nucleus and binds to FBW7 after TKI treatment, which leads to the degradation of MCL1." (PMID 39122703, 2024). "A CBRN ligand-based ALK PROTAC was shown to cause degradation of NPM-ALK and EML4-ALK in lung cancer lines at certain thresholds." (PMID 38835344, 2024). "Agents, such as EGFR tyrosine kinase inhibitors (TKIs) and ALK inhibitors, have changed the treatment paradigm for patients with actionable mutations, providing a personalized approach to systemic therapy for lung cancer bone metastases." (PMID 39766043, 2024).
lung cancer (continued). "In this paper, we report a case of PMEC-based primary lung cancer combined with ALK mutation, and discuss the key issues of clinical diagnosis and treatment in the light of relevant literature review." (PMID 39259069, 2024). "We presented a case of ALK‐positive lung cancer with diffuse liver metastasis causing liver failure, where severe hemolytic anemia was induced by low‐dose alectinib." (PMID 39527462, 2024). "All non–small-cell lung cancers (NSCLCs) with epidermal growth factor receptor (EGFR) or anaplastic lymphoma kinase (ALK) mutations who received TKIs between 2015 and 2019 in Qatar were included." (PMID 39416762, 2024). "NSCLC is the predominant form of lung cancer, with ALK gene mutations accounting for approximately 5% of NSCLC cases." (PMID 38274094, 2023). "Lung cancer patients with ALK-rearrangement or EGFR mutations had lowest proportion of PD-L1+/CD8+ tumors and the shortest overall survival." (PMID 36874015, 2023). "Patient #2 with the same diagnosis and ALK variant had a great-grandfather with lung cancer in advanced age and a great-uncle with laryngeal cancer in the forties." (PMID 38139220, 2023). "The ALK mutation is known as the “diamond mutation,” and treatments for ALK rearrangement-positive nonsmall cell lung cancer recommend alectinib, brigatinib, or lorlatinib as first-line therapy, with ceritinib or ceritinib as secondary alternatives." (PMID 37250453, 2023). "The clinical efficacy of targeted therapy in ALK gene fusion lung cancer patients was validated, and the drug susceptibility detection results from all organoids were consistent with the clinical response (100%, 5/5)." (PMID 37941550, 2023). "FDA-approved drugs like osimertinib and crizotinib specifically inhibit these aberrant pathways, providing remarkable benefits in patients with EGFR-mutated or ALK-positive lung cancer." (PMID 37686423, 2023). "Except for smoking history, better performance status at the last follow up and targeted therapy for EGFR or ALK mutation significantly improved survival rates for metastasis of lung cancer." (PMID 37510797, 2023). "Precision therapy with oncogene-targeted drugs has dramatically changed the outcomes for lung cancer patients with tumors positive for mutated EGFR or fusion kinases including ALK and ROS1 and others." (PMID 36845684, 2023). "Such challenges are evident in anaplastic lymphoma kinase (ALK)-rearranged lung cancers, where mutations, alternative activation pathways, and epigenetic shifts are observed." (PMID 38239350, 2023). "The feasibility of the proposed model was verified for rare ALK mutation cases and ALK-targeted drugs by accumulating a lung cancer PDO library." (PMID 37993887, 2023). "ALK gene mutations have been found in some types of cancer, including neuroblastoma, non‐small cell lung cancer, and anaplastic large cell lymphoma." (PMID 36746394, 2023). "Several trials showed similar PFS benefits over chemotherapy using ALK-TKIs between smokers and never-smokers for patients with treatment-naïve advanced stage ALK mutation-positive lung cancer." (PMID 37007097, 2023). "Alectinib has been reported to be effective for crizotinib‐resistant ALK mutation, including L1196M gatekeeper mutation, and shows objective responses in crizotinib‐resistant ALK‐rearranged non‐small cell lung cancers (NSCLCs)." (PMID 36819147, 2023). "In our study, age was the only preoperative clinical feature notably associated with ALK-positive early-stage lung cancer." (PMID 36823653, 2023).